VTRNA3-1P (vault RNA 3-1, pseudogene)
Synonyms: vtRNA3P; hvg-4; HVG4; HVGX; VAULTRC4
Gene: Miscellaneous RNA gene on chromosome X (53,462,209 to 53,462,310, forward strand). Ensembl gene ENSG00000199422.
Homologues: Orthologues: chimpanzee Vault (98% identical), guinea pig Vault (61% identical). Paralogues in human: VTRNA1-1 (75% identical), VTRNA1-2 (64% identical), Vault (64% identical), VTRNA1-3 (63% identical), VTRNA2-2P (51% identical), Vault (48% identical), Vault (45% identical).